FOXA1 (forkhead box A1)
Diseases named in the same sentence as FOXA1 in open-access papers (continued):
Sharing a sentence is not in itself a finding about the gene and the disease.
tumor (continued). "We report the findings of additional morphological abnormalities in the Stat1−/− mouse that reflect systemic endocrine and environment effects, as well as the identification of a FoxA1+ large oval pale (LOP) cell that appears along some Stat1-null ducts as their hosts approach tumor-bearing age." (PMID 28865492, 2017). "In this sense it will be also very interesting to explore the expression of CTR in primary and metastatic MTC lesions, as well as in the invasive front vs tumor bulk, in combination with lineage specific markers (Foxa1/Foxa2) and epithelial–mesenchymal transition markers." (PMID 28929017, 2017). "NSCLC tissue had significantly higher levels of FOXA1 mRNA than paired non-tumor tissue (p < 0.01)." (PMID 26909612, 2016). "FOXA1 staining levels in primary tumor samples were detected using immunohistochemistry." (PMID 26986977, 2016). "Notably, Foxa1 was predominantly nuclear in loosely coherent cells but mostly cytoplasmic in more crowded nests of tumor cells." (PMID 26395490, 2015). "Moreover, we also observed that FOXA1 expression was significantly lower in BRCA1-mutated tumours compared with BRCA2, BRCAx and BRCA2/x tumours (P<0.001, P=0.001 and P<0.001, respectively; Student's t-test)." (PMID 25531315, 2015). "In conclusion, miR-212 may serve as a prognostic indicator for HCC patients and exerts tumor suppressive role, at least in part, by inhibiting FOXA1." (PMID 25965836, 2015). "In vivo xenograft model, FOXA1 knockdown reduced the rate of tumor growth." (PMID 24512546, 2014). "With this observation in mind, we hypothesized that functional expression of FOXA1 might induce tumor metastasis in EC." (PMID 24512546, 2014). "On the other hand, FOXA1 has been reported to act as a tumor suppressor." (PMID 24512546, 2014). "Loss of steroid receptor and Foxa1 expression in MMTV-NeuNT tumors indicated that Erbb2 expression drove the loss of these markers and that their loss may be associated with tumor etiology." (PMID 23593223, 2013). "Furthermore, FOXA1 staining of a TMA consisting of metastatic tumor deposits from positive lymph nodes dissected from 28 patients represented in the primary tumor TMA revealed a further association between FOXA1 loss and SCC." (PMID 22590586, 2012). "The prevalence of FOXA1 expression decreased with increasing tumor stage." (PMID 22590586, 2012). "Foxa1 was also implicated in cell cycle regulation in tumor-derived cells, but a mechanistic model was not established." (PMID 22737085, 2012). "The combined evidence supports the connection between FOXA1 and tumor progression in PC." (PMID 22879989, 2012). "This indicates that although approximately 80% of T2–T4 SCCs are negative for FOXA1, SCC are not the only cancers that show FOXA1 loss and advanced tumor stage." (PMID 22590586, 2012). "Interestingly, only the RT4 cell line, which was originally propagated from a well differentiated tumor, exhibited high FOXA1 expression." (PMID 22590586, 2012). "Further dissection of the contribution of FOXA1 to dictation of tumor cell and metastatic outcome, and of its mechanism of action, may provide new opportunities for therapeutic targeting of advanced stages of PC." (PMID 22879989, 2012). "Nonetheless, we observed strong correlations between ER and many genes that have previously been shown to be strongly associated with ER positivity, including GATA3, FOXA1, AGR2, AR, and STC2, in microarray profiling studies of mixed ER-positive and ER-negative tumours." (PMID 17555561, 2007).
tumor (continued). "These HNF4G-restricted FOXA1 metastasis genes were correlated well with the gene expression profiles of metastatic patient samples (mets) when compared to a cohort of classical subtype primary tumor samples (from the PanCuRx dataset), validating the conclusion from the preclinical models." (PMID 41168397, 2025). "Therefore, while HNF4G is the dominant transcription factor in primary tumor contexts, a switch occurs in advanced disease, resulting in engagement of FOXA1 to enhancers that create spatial genomic re-organization and ultimately in induction of metastasis-specific gene targets." (PMID 41168397, 2025). "This suggested that FKH domain mutations in FOXA1 do not exhibit lineage plastic profiles that may affect the tumor microenvironment (TME)." (PMID 39745364, 2025). "Additionally, four tumor gene mutation-related indicators, including APOBEC Enrichment score, MATH score, TCW score, and TMB score, were all significantly higher in patients with low FOXA1 expression." (PMID 39440050, 2024). "Therefore, by inhibiting FOXA1, miR-204 acts as a tumor suppressor promoting cell death." (PMID 39199587, 2024). "Among seven potential tumor-suppressing miRNAs identified in this study, high expression of miR-100 was associated with better outcomes in women with luminal A tumors treated with adjuvant endocrine therapy and was inversely linked to mRNA expression of PLK1, FOXA1, mTOR, and IGF1R." (PMID 37508580, 2023). "This could explain the limited infiltrate of luminal tumours, expressing high levels of FOXA1." (PMID 36944729, 2023). "Indeed, it is still unknown how FOXA1 alterations affect the prognosis in human cancers, and how FOXA1 is able to serve as both tumor-suppressor and oncogenic genes." (PMID 37876590, 2023). "The possible explanation could be that FOXA1, as a strong activator of E-cadherin transcription, could serve as a tumor suppressor gene which could possibly reverse EMT by increasing E-cadherin expression, restoring the epithelial phenotype of the cancer cells." (PMID 36393971, 2022). "Consequently, forced expression of FOXA1 hampered the efficacy of anti-angiogenesis reagent against A549 xenograft tumor, which could be restored by combinatory treatment with IGF1R inhibitor." (PMID 35974000, 2022). "Therefore, the functions of FOXA1 as an oncogenic gene or tumor suppressor are still controversial." (PMID 34336665, 2021). "Interestingly, Sample_15, a Gleason pattern 4 tumour, shows high enrichment for FOXA1, HOXB13 and CDX2, followed by Fra1/2, Atf3, JunB and AP-1 binding sites enriched in Gleason pattern 3 tumours, suggesting a transitionary state between the two regulatory states." (PMID 34911933, 2021). "Previous studies have shown that FOXA1 expression was inversely associated with tumor size, histological grade, lymph node status, HER2 expression and lymph vascular invasion, while GATA3 expression showed an inversed association with tumor histological grade and HER2 status." (PMID 30819139, 2019). "Six genes (including genes encoding ER, PR, HER2 and their transcription factors MYC, FOXA1, MYBL2) were removed from PAM50 (the new panel is named PAM50–6) to exclude their confounding effect on the classifier, as the ground truth was based on tumor classification stratified by ER, PR and HER2." (PMID 31699026, 2019). "Therefore, the correlation of FOXA1 expression with luminal A tumours could explain lower expression of TOX3 in our study and poorer survival of carriers of the rs3803662 risk allele and luminal A tumours." (PMID 23270421, 2012). "While the overexpression of FOXA1 and HOXB13 pushes AR cistrome to a more tumor-like profile, pioneering activity of GATA2 allows AR to bind to enhancers of metastasis and treatment resistance associated genes, thereby contributing to PCa progression." (PMID 40833121, 2025).
tumor (continued). "Our data suggest that multiple mechanisms exist for a tumor to inhibit HNF4G activity, allowing FOXA1 to become active and drive metastatic spread." (PMID 41168397, 2025). "This provides a strong complement to the mechanism of NOTCH pathway activation in LUAD, suggesting that targeting the FOXA1/NOLC1 axis is an effective way to regulate LUAD NOTCH pathway and suppress tumor cell stemness." (PMID 39789998, 2025). "Tumor organoids also established syngeneic allografts in C57BL/6 host mice while retaining their adenocarcinoma histology and expression of transgenic FOXA1, AR, and CK8 luminal markers." (PMID 40570057, 2025). "Our research identified a significant downregulation of FOXA1 in NPC tissues and cell lines, which correlates with advanced clinical stages and poor differentiation, underscoring its potential role as a tumor suppressor." (PMID 40623983, 2025). "In the primary tumor context, HNF4G was the dominant transcription factor that drives tumor growth, while also negatively regulating FOXA1 transcriptional activity." (PMID 41168397, 2025). "ACSL5 was found to function as an immune-dependent tumor suppressor, and SPDEF and FOXA1 are the canonical markers of mammalian “goblet cells”." (PMID 40429746, 2025). "By suppressing forkhead box A1 and sonic hedgehog signaling, activated AMPK prevents the growth of tumor cells and triggers apoptosis." (PMID 40439888, 2025). "Prior studies have reported significant downregulation of FOXA1 in NPC tissues and cell lines, correlating with advanced clinical stages and poor differentiation, which suggests its potential as a tumor suppressor." (PMID 40623983, 2025). "To explore and validate the potential role of FOXA1 in PDAC, we conducted an orthotopic tumor experiment." (PMID 41168397, 2025). "Our data so far suggest that HNF4G can cobind with FOXA1 to the same genomic regions, but only HNF4G is essential for tumor growth, in part, by recruitment of PRMT1." (PMID 41168397, 2025). "MYC, FOXA1, HIF1A, PAM50 and both ROR are determined at the gene expression level in RNA extracted from FFPE tumor tissue using the nCounter platform." (PMID 40997111, 2025). "Pharmacological targeting with SR8278 diminishes the function of both REV-ERBα and FOXA1 and synergizes with BRD4 inhibitor in effective suppression of tumorigenic programs and tumor growth." (PMID 39383000, 2024). "During tumor progression, some authors have found that AGR2 and FOXA1 are recognized as prognostic markers during tumor progression, with both proteins interacting and mutually promoting each other at low levels." (PMID 39062458, 2024). "Examining TF regulatory networks, FOXA1 and FOXA2 promoter and enhancer regions were hypomethylated when compared to non-tumor control tissue." (PMID 38173042, 2024). "FT282-C11 cells have low expression of FOXM1, FOXM1-P (activated FOXM1), CCNB1 (canonical FOXM1 target), FOXA1, and FOXK2 (all oncoproteins), and elevated FOXO3a (a tumor suppressor), as compared to HGSOC cells, validating their utility as a normal control." (PMID 38704607, 2024). "Among the 991 BC tumor samples, GATA3 had the highest frequency of somatic SNVs, accounting for 13%; followed by FOXA1, accounting for 3%; AGR2, CA12, CEP55, CDC20, TBC1D9, and MELK had very few somatic SNVs." (PMID 39440050, 2024). "In summary, a correlation exists between FOXA1 and HER2 in the tumor tissues of patients with advanced NSCLC." (PMID 39440051, 2024).
tumor (continued). "Further mechanistic research confirms that RC48 not only regulates the HER2/PI3K/AKT signaling pathway but also the FOXA1/HER2/PI3K/AKT signaling pathway, exerting a potent anti-tumor effect." (PMID 39440051, 2024). "Other AR-related genes (FOXA1, NCOA2, SPOP) exhibited minimal differences in transcript expression in either metastatic site relative to the primary tumor." (PMID 39349591, 2024). "Here, we found the overexpression of FOXA1 and HOXB13 alone, or in combination, to markedly shift the AR cistrome away from full AREs (normal-like) towards chimeric AR half elements in the tumor-like state." (PMID 39251788, 2024). "The peaks of epithelial cells and tumor cells were notably enriched in the gene sets of ‘VIM, KRT5, KRT17’ and ‘KRT8, KRT18, FOXA1’, respectively." (PMID 38581422, 2024). "Studies have found that FOXA1, FOXM1, FOXO3, FOXP1, and so on play an important role in tumors as oncogenes or tumor suppressor genes." (PMID 38608123, 2024). "In addition to the tumor microenvironment, analyses of data from The Cancer Genome Atlas database show distinctive molecular aberrations in ILC compared with IDC, such as E-cadherin loss (66% vs. 3%), FOXA1 mutations (7% vs. 2%), and GATA3 mutations (5% vs. 20%)." (PMID 38180699, 2024). "The high expression of mRNA in FOXA1 (P < .05), FOXM1 (P < .01), and FOXP1 (P < .05) groups was related to tumor stage." (PMID 38608123, 2024). "FOXA1 and FOXA2 play different biological functions in tumor development by regulating the expression of multiple genes, which are closely related to cancer development and chemoresistance." (PMID 38605023, 2024). "Tumour cells showed enrichment of hepatocyte differentiation‐related TFs HNF4A/G and FOXA1/2,44 and highly expressed targeted genes of these TFs." (PMID 39210544, 2024). "Tumor was resected and analyzed by H&E staining and expression of luminal markers estrogen receptor alpha (ERα), GATA3, and FOXA1 and cytokeratins CK5/6, CK8, CK14 and CK19 was examined." (PMID 37709737, 2023). "For instance, FOXA1, NWD1 and MAZ have been shown to promote tumor progression by modulation of androgen receptor expression and are frequently linked with poor prognosis." (PMID 36818049, 2023). "It is worth noting that FOXA1 target genes were mainly enriched in pathways related to apoptosis, mitosis, mTOR, TNF-α, indicating its possible involvement in tumor malignant proliferation and supporting our fold enrichment of CERES scores above." (PMID 37876590, 2023). "Treatment of xenograft mice with the SKP2 inhibitor SZL P1‐41 decreased tumor proliferation, SKP2:FOXA1 ratios, and colocalization." (PMID 37491794, 2023). "Specific genes and pathways, such as FOXA1 and Sonic hedgehog (SHH), have been shown to contribute to tumor metastasis." (PMID 36916531, 2023). "FOXA1, FOXM1, FOXO subfamily genes, and FOXR1 have been widely studied and confirmed to promote tumor progression through various pathways, such as proliferation, invasion, and immunity." (PMID 37563111, 2023). "Functional experiments in our study revealed that FOXA1 promoted CC cell resistance to DDP in vitro and facilitated tumor growth in vivo by upregulating SIX4 expression and activating the PI3K/AKT signaling." (PMID 35498155, 2022). "Yet, there is still insufficient work to illustrate the mechanism regarding the promotive effects of FOXA1 on EMT and further tumor microenvironment (TME) in EOC." (PMID 36393971, 2022).
tumor (continued). "Expression analysis revealed that HPV integration disrupted gene expression, but the upregulation of CD274, PDCD1LG2, FOXA1, and TNFSF4 provided opportunities for tumor immunotherapy." (PMID 35392231, 2022). "These tumours also express other luminal markers (XBP1 and FOXA1) but lack the expression of basal cytokeratins." (PMID 36077812, 2022). "We provide evidence that the protective role of FOXA1 on LUAD cells is highly dependent on induction of IGF2, which is a multifunctional growth factor that promotes tumor cell survival via activating IGF1R signaling cascade." (PMID 35974000, 2022). "Further studies showed that lncRNA RGMB-AS1 inhibited tumor proliferation and EMT by directly binding to FOXA1." (PMID 35184697, 2022). "CTCs isolated from patients with ABI- or ENZ-resistant metastasis showed amplification in the FOXA1 gene in > 30% of CRPC patients, pinpointing the crucial role of FOXA1 in AR regulation and tumor progression." (PMID 36176747, 2022). "Previous studies have also demonstrated that FOXA1 and FOXD1 are broadly involved in tumor development as well as mitochondrial metabolism." (PMID 36585925, 2022). "Tumor tissues were fixed with formalin, embedded in paraffin, and stained with H&E and IHC to detect HDAC3 and FOXA1 expression." (PMID 34991620, 2022). "GATA3, FOXA1, RASSF5, PTPN6, and TRNP1, involved in the luminal markers and negative regulation of cell proliferation, are related to tumor suppression and chemotherapy resistance." (PMID 36344487, 2022). "It is reported that the expression of FOXA1 is relatively higher in both HCC tissues and human hepatic cell lines than non-tumor tissue and cells." (PMID 34336665, 2021). "Finally, we found that expression for the chromatin factor ANP32E was anti-correlated with tumor progression and with accessibility at FOXA1 binding sites among group 2 and 3 tumors, suggestive of a novel mechanism by which FOXA1 activity may be regulated in breast cancer tumors." (PMID 34922480, 2021). "For instance, we demonstrate lncRNA MCM3AP-AS1 as a tumor-promoting factor in HCC, and it promotes cancer cell growth by sponging miR-194-5p to enhance forkhead box A1 (FOXA1) expression." (PMID 34093813, 2021). "Forkhead box protein A1 (FOXA1) is a pivotal transcription factor involved in cell proliferation, apoptosis, and differentiation, organogenesis, and tumor progression." (PMID 34419060, 2021). "Conversely, downregulation of FOXA1 in MCF-7 and T47D cells led to a decrease in both the number of tumor initiating cells in the mammosphere formation and soft agar assays." (PMID 33417085, 2021). "They predominantly flank the loci harbouring FOXMIND-FOXA1 as FOXA1 and FOXMIND are co-duplicated in 89% of the tumours with tandem duplications, driving aberrant FOXA1 and MIPOL1 mRNA expression." (PMID 32946061, 2021). "Several recent studies have proposed various mechanisms of NEPC development, including modifications of the tumor microenvironment with epigenetic effects on cancer cells, as well as reports of molecular drivers such as SRRM4, FOXA1 and ONECUT2." (PMID 32252342, 2020). "Our results indicate that FoxA1 was down-regulated in CCA and had tumor suppressive roles in CCA progression; therefore, down-regulation of FoxA1 in CCA tissues was related with poor prognosis." (PMID 32151057, 2020). "A study of matched normal, early neoplasia and carcinoma from a cohort of 25 women identified elevated expression of ERBB2, FOXA1, and GATA3." (PMID 31248446, 2019). "In this principal examination of SHRs, FOXA1 and GATA3 in a tumor series, we observed these two ERα-regions were bound by all other factors." (PMID 29396493, 2018). "In our study, patients with AR + /FOXA1 + tumours had a shorter RFS and OS than other TNBC and AR/FOXA1 co-expression was an independent prognostic factor for OS." (PMID 29880907, 2018). "Among patients with a PD-L1 + tumour, we found significantly poorer RFS and OS in case of AR/FOXA1 co-expression." (PMID 29880907, 2018).